MYB (MYB proto-oncogene, transcription factor)
Diseases named in the same sentence as MYB in open-access papers (continued):
Sharing a sentence is not in itself a finding about the gene and the disease.
cancer (continued). "Our findings demonstrated that RSL3 acted as MYB inhibitor in MDS cells, and it is worth to explore whether this mechanism is conserved in other cells, especially in MYB-induced cancer." (PMID 38956026, 2024). "MYB had a strong correlation with B cell in 24 cancer types, CD4 T cell in 22 cancer types, CD8 T cell in 18 cancer types, neutrophil in 25 cancer types, macrophage in 13 cancer types and DC in 24 cancer types." (PMID 36994664, 2023). "MCL-1 upregulation may also play a significant role in cancer cell survival and drug resistance in ACC with MYB overexpression." (PMID 37511133, 2023). "While known driver mutations in MYB and the activation of Notch are not actionable targets right now, we have identified the BCL2 gene overexpression solely in LGACC cancer cells that has small molecular inhibitors including Gossypol and Disarib." (PMID 37370820, 2023). "Furthermore, MYB is often up-regulated in patients with CRC, and recently have gained increased attention as a potential and novel therapeutic target in cancer." (PMID 35600365, 2022). "Using qPCR assay for known genes modulated NT157 in other cancer models, we identified that NT157 decreased expression of oncogenes BCL2, CCND1, MYB, and MYC and increased genes related to cellular stress and apoptosis, JUN, BBC3, CDKN1A, CDKN1B, FOS, and EGR1 (all p < 0.05)." (PMID 36224313, 2022). "Therefore, this study sets to examine the role of nsSNPs of MYB, MYBL1, and MYBL2 genes through bioinformatics tools in understanding its pathogenesis toward cancer." (PMID 34921182, 2021). "Importantly, the key cancer-drivers/oncogenes MYC, MYB and AR were suppressed by TSPX in a CAD-dependent manner." (PMID 30863497, 2019). "Some of the genes, for example, TSN and MYB, are potential regulators of proliferation and so this could indicate that TEX19 is required by cancer cells to drive proliferation by maintaining sufficient levels of oncogenic transcripts." (PMID 28446200, 2017). "In some cancers this involves amplification of the MYB gene and increased c-Myb expression." (PMID 26208222, 2015). "It has been documented that C-MYB (MYB) plays different roles in normal and cancer cells." (PMID 24639887, 2014). "Conversely, enforced MYB expression was able to block differentiation of both carcinoma cells and non-tumorigenic HC11 cells, again strikingly paralleling the activities of MYB in other cell systems." (PMID 20659323, 2010). "Therefore, MYB, HDAC2, and FOXA2 are master regulators in controlling the Boolean GRN model toward an enterocyte state and could be effective targets for cancer treatment." (PMID 39661721, 2025). "However, the prognostic value and immunity of MYB in various human cancers is not clearly elucidated." (PMID 36994664, 2023). "Furthermore, miR-150 regulates cancer cell migration by affecting multiple effectors including matrix metalloproteinases (MMP14 and MMP13), cell adhesion molecules (ITGA3, ITGA6), transcription factors (MYB), and epigenetics factors (HMGA2 and EZH2)." (PMID 37924077, 2023). "When we compared the correlations between MYB expression and its targets in the 2KR-MYB set that are also defined as direct 2KR-MYB targets, we observed even stronger correlations, 87.3%, 91.0%, and 89.7% in the LAML, BRCA, and COAD cancer cohorts, respectively." (PMID 37468105, 2023). "Notably, MYB, KIT, and FABP7 (the top-ranked signature genes) directly interact with NOTCH1, and these interactions have been reported to be involved in regulating cancer stem cell differentiation." (PMID 36879115, 2023). "Interestingly, cancer cells that express c-MYB and do not express pVHL are the ones that can take advantage of the MYBBP1A knock down." (PMID 30781655, 2019). "Interestingly, cancer cells that express c‐MYB and do not express pVHL are the ones that can take advantage of MYBBP1A downregulation." (PMID 31066170, 2019).
cancer (continued). "However, there is evidence in the literature suggesting an activation of miR-200s by c-MYB32 which suggests that the relationship between miR-200s, c-MYB and EMT is complex and maybe even cell type or the cancer microenvironment dependent." (PMID 31827114, 2019). "In addition, though MYB is considered as an oncogene in AML with a potential super-enhancer, the candidate MYB-SE was not present in AML and many other cancer types (Fig. EV1E)." (PMID 40234694, 2025).
infection (92 papers, 2004 to 2025). The state of being infected such as from the introduction of a foreign agent such as serum, vaccine, antigenic substance or organism. "We found that a higher proportion of the DEGs encoding EREB, bHLH, NAC, and MYB TF families were enriched in DEGs associated with the infection of Mite herbivores." (PMID 38816789, 2024). "In the present study, we found that the expression levels of some MYB transcription factors changed significantly in the resistant and susceptible materials after infection by Rhizoctonia cerealis." (PMID 35534832, 2022). "From the studied factors, the MYB and bHLH transcription factors were mostly down-regulated by infection in cones and these differences can cause expression differences for biosynthesis pathways genes." (PMID 34834660, 2021). "The most strongly repressed genes in S23 infection encoded TFs from MYB and basic helix-loop-helix (bHLH) families, carotenoid isomerase, flagellar biosynthesis protein, and DNA-directed RNA polymerase subunit beta, among others." (PMID 31671783, 2019). "Similarly, MYB TFs have been linked to nodulation through their involvement in root hair infection and meristem formation, as seen in LjMYB14, which regulates flavonoid biosynthesis essential for rhizobial interaction in Lotus japonicus." (PMID 41240368, 2025). "MYB transcription factors are among the most abundant and versatile transcription factors in plants, playing a positive regulatory role in the process of hypersensitivity response caused by pathogen infection." (PMID 40001489, 2025). "This may indicate that MYB-driven responses may vary according to the strain of geminivirus causing the infection, or the cultivar being tested." (PMID 36494781, 2022). "On the other hand, a lower number of DEGs encoding WRKY or AP2/ERF members were observed after infestation by HSt or FDSt in T. friulano, while a significant modulation of genes encoding MYB transcription factors occurred after FDSt infection, both at 3 and 6 dpi." (PMID 31242866, 2019). "The identification of large number of transcripts coding for PR proteins, receptor-like proteins, NBS-LRR and transcription factors (such as WRKY and MYB) shows that even a susceptible citrus genotype is able to actively respond to infection by CaLam, as reported for CaLas." (PMID 23586643, 2013). "Recently, several authors have indicated the essential role of MYB TFs in primary and secondary metabolism, hormone synthesis, signal transduction, and against pathogen infection." (PMID 40700398, 2025). "Several families of TFs, including Ethylene Response Factor (ERF), MYB, NAC, basic Helix-Loop-Helix (bHLH), and Auxin Response Factor (ARF), have been implicated in various stages of nodulation, from rhizobial infection to mature nodule function." (PMID 41240368, 2025). "MYB supports root hair infection and flavonoid biosynthesis, WRKY is involved in metabolic defense regulation, and bHLH influences root architecture and rhizobial attachment." (PMID 41240368, 2025). "Four TF families, the WRKY, NAC, AP2/ERF, and MYB families, that represented a total of 209 master regulator gene candidates induced along infection progress, were distinguished for their central role in FHB responses." (PMID 38443953, 2024). "Results from this study showed that MYB-related GO terms are over-represented in both FCR infection and drought stress." (PMID 38286831, 2024). "In our analysis, MYB TF was up-regulated in the susceptible genotypes Graciosa and Semper in response to BYDV-PAV infection at 10 dai, and the up-regulation remains less pronounced at 30 dai." (PMID 36992425, 2023). "Recently, numerous researchers have found that MYB TFs play vital roles in signal transduction, hormone synthesis, primary and secondary metabolism, and against pathogen infection." (PMID 37231351, 2023).
infection (continued). "By activating synthesis of phytoalexin 3-deoxyanthocyanidin at the site of primary infection, the MYB transcription factor of sorghum enhances the resistance of maize to verticillium wilt." (PMID 37991550, 2023). "S1_218 was located in the CDS region of Zm00001d032244 (probable inactive receptor kinase) and A MYB-transcription factor 146 (Zm00001d032240) was located 110kb upstream; Zm00001d032240 is notably upregulated after infection by Cercospora zeina." (PMID 37810381, 2023). "MYB transcription factors have been reported to play a key role in response to the infection of the root parasitic weed O. cumana on the sunflower." (PMID 37007956, 2023). "In the current study, we observed a significant upregulation of the RLK, WRKY, AP2/ERF, and MYB families following pathogen infection, suggesting their potential involvement in the response to MR-9 infection." (PMID 37628875, 2023). "The MYB TFs also play crucial roles in regulating the responses against infection by pathogens, such as bacteria and fungi." (PMID 37231351, 2023). "Transcription factors classified as BBX-DBB, BBX-CO, DOF, MYB, REVEILLE, bZIP, NPL, ERF, AP2, NAC, and bHLH were revealed as differentially expressed in the susceptible cultivar during the BBTV infection process." (PMID 37907581, 2023). "Combined with the results of a GO analysis, four MYB TFs that were involved in phenylpropanoid biosynthesis were noted, and an RT-qPCR analysis showed that they were significantly up-regulated in the infection process." (PMID 36844070, 2023). "The enhanced expression pattern of the transcription factors, including WRKY and MYB, during later stages of infection in Ss97009, was also found to implicate their significance in transcriptional reprogramming during disease development." (PMID 36325538, 2022). "Then, the expression of three pathogenesis-related (PR) genes and seven MYB genes in rhizomes during postharvest storage and subjected to pathogen infection was normalized by RBP, ATPase, 40S_S3, RBP and ATPase, ATPase and 40S-S3, and RBP and 40S-S3." (PMID 35734245, 2022). "The results showed that PR and MYB genes were induced by postharvest deterioration and pathogen infection." (PMID 35734245, 2022). "In this study, a large number of AP2, WRKY and MYB transcription factor family genes were involved in the response of mycorrhizal plants against infection with F. solani." (PMID 35918651, 2022). "Two significantly up-regulated MYB genes (Cla97C08G148320 and Cla97C01G012490) were identified from our data, which were suspected to be involved in the protection against the infection of root-knot nematode." (PMID 35888092, 2022). "It is worth mentioning here miR858 has been shown to negatively regulate MYB transcription factors, thereby controlling resistance to pathogen infection in A. thaliana." (PMID 34380425, 2021). "More recent studies showed that SA promoted the biosynthesis of flavan-3-ol and PAs in Poplar by activating the MYB-bHLHWD40 complex against rust proliferation and infection." (PMID 31699028, 2019). "The expression of MYB genes showed variation from the infection phase to the production phase, but many of them peaked at 1 dpi." (PMID 31569685, 2019). "The transcription of this MYB gene was also up-regulated in B. sorokiniana-resistant wheat Yangmai 6 after infection of B. sorokiniana." (PMID 28496196, 2017). "On the other hand, NAC and MYB, with demonstrated roles in plant defense responses to various environmental stresses, were also strongly induced by HG type 2.5.7 infection." (PMID 28852059, 2017). "After infection, 31 MYB genes and 18 NAC genes were significantly induced, the expression levels of 17 MYB genes and 13 NAC genes were significantly up-regulated in S54." (PMID 28852059, 2017). "Our study provided new insight into functional diversity of MYB TFs in plant defense responses to infection of different pathogens." (PMID 28496196, 2017).
infection (continued). "Identification and characterization of full-length cDNA sequence of wheat MYB gene TaPIMP1 against pathogen infection by using RT-PCR, RACE, and its overexpression in transgenic tobacco under drought and salt stress have also been studied." (PMID 29181384, 2017). "NAC, MYB, and zinc finger TF family members are primarily responsive to pathogen infection and abiotic stress." (PMID 26734057, 2015). "The upregulation of NAC and MYB in the early stage of infection may play an important role in Zhonghua 6 to A. flavus infection." (PMID 37505683, 2023). "Therefore, MYB transcription factors play important roles in the response to infection by Rhizoctonia cerealis." (PMID 35534832, 2022). "In addition, transcription factor families such as bHLH, SBP, AP2, WRKY, and MYB were detected in response to infection." (PMID 35627172, 2022). "Similarly, some MYB genes which are reported to participate in defense responses were induced after infection with different pathogens." (PMID 36430549, 2022). "In accordance with recent studies that identified transcription factors differentially expressed for mild and severe infection in two pepper cultivars, our results show that MYB-TFs, Homeodomain, WRKY, and heat-shock-related are specific for the severe condition." (PMID 35682662, 2022). "MYB TFs also played important roles in response to pathogen infection." (PMID 33705404, 2021). "Previous studies, 24 reported that 4 wheat MYB genes, including TaPIMP1, TaMYB4, TaLHY, and TaRIM1, positively participate in infection of the soil-borne fungal pathogen B. sorokiniana, the biotrophic fungal pathogen Pst, and the necrotrophic pathogen R. cerealis, respectively." (PMID 28496196, 2017). "In addition to their other functions, it is known that both MYB and bZIP transcription factors have roles during pathogen infection." (PMID 26076360, 2015). "In addition to having regulatory roles in the defense response upon infection with different pathogens, several MYB genes have been reported as key regulators of sugar-responsive genes, such as α-amylase during sugar starvation in rice." (PMID 23586643, 2013). "Ideally, these observations would be validated in knockout models; however, MYB loss in a c-myb knockout murine model impeded the formation of stem cell-like TCM CD8+ T-cells with loss of Bcl-2 and massive apoptosis of CD8+ T-cells in the initial immune response to infection." (PMID 41232235, 2025). "In addition, differentially expressed genes encoding transcription factors from the MYB, NAC, WRKY, ERF, and bHLH families were highly expressed, they could be the key responsive factor in the response of cherry to infection by A. alternata." (PMID 36844070, 2023). "The infection brought by P. viticola appeared to elicit a co-ordinated and sequential transcriptional activation of distinct stilbene synthase genes subsets, each of which may be regulated by a distinct and specific MYB transcription factor." (PMID 31521112, 2019). "The enrichment analysis showed that TF’s NAC, MYB, bHLH, ERF C2H2, WRKY, and bZIP were up-regulated in Eucalyptus leaves mainly at the late stage of infection by T. destructans." (PMID 40788552, 2025). "Upon detection of pathogen infection by immune receptors such as CC-NBS-LRR proteins, transcription factors, particularly from the WRKY and MYB families, play a role in the transcriptional regulation of defensive response genes." (PMID 39852460, 2025). "Through this re-localization, STAT3 regulates downstream transcription factors MYB and BLIMP-1 in an inflammation-dependent manner to shape NK cell differentiation under homeostasis and during infection." (PMID 41040338, 2025). "The MYB transcription factor (TF), i.e., GAMYB for barley, was up-regulated in Graciosa in response to BYDV-PAV infection at 10 dai and less markedly at 30 dai." (PMID 36992425, 2023).
infection (continued). "Most of them belonged to the MYB, bHLH, WRKY, NAC, LUX and GLK TF families and presented high increment or decrement after FOC infection." (PMID 35698057, 2022). "For example, the largest group of pathogen-induced TFs belongs to the WRKY family, which is well known for plant defense, and several MYB, NAC, and bHLH family members were also induced during infection." (PMID 36008749, 2022). "Upon cis-regulatory motif detection, we detected significant overrepresentation of HD, ARID, CXC, MYB, SANT/MYB, NAC and AT-hook binding motifs within TE sequences of EPRV and hAT in multiple infection-related conditions." (PMID 34983397, 2022). "Other MYB genes that control GS synthesis, such as MYB28, MYB29, and MYB34 were also down-regulated in the iqd1-1 line but only after infection with B. cinerea." (PMID 35557724, 2022). "Two MYB transcription factors (MELO3C009678 and MELO3C014597) responded to the fusarium wilt (Race 1) infection signal by showing the opposite regulatory patterns." (PMID 35937314, 2022). "In the present study, 305 TFs belonging to 24 major transcription factor families were differentially expressed after FBS infection, mainly bHLH, NAC, MYB, and WRKY." (PMID 36232919, 2022). "Many phytohormone-related genes and transcription factors (MYB, WRKY, and NAC) were differentially expressed at the four time points (ck, 7, 14, and 28 days post-infection)." (PMID 33924485, 2021). "We focused our attention on four TFs families that are known to contribute to environmental stress responses in plants NAC, MYB, bZIP, and AP2/ERF noting that there was between 1.5- to 8-fold increase in gene expression due to PVX-GFP infection." (PMID 33799566, 2021). "In U 4-7-5 genotype, upon infection, a few TFs families such as ARF, DBB, MYB, NAC and C2H2 were found to be highly upregulated compared to JL 24 upon infection." (PMID 33339393, 2020). "The expression of many TFs genes including AP2/ERF, MYB, bHLH and WRKY can be induced by a variety of biological and abiotic stresses, such as high salt, drought, low temperature, plant hormones, pathogen infection and so on." (PMID 32635887, 2020). "Genes activated by infection corresponded to transcription factors (e.g., AP2/ERF, MYB, WRKY and NAC) and synthesis of defense-related metabolites, including pathogenesis-related genes, glucosidase and dehydrin." (PMID 31083412, 2019). "At the late stages of infection (infection index >10), we observed induction of several meiosis-related genes, including HOP1 and MND, two SPO11 homologues and MYB in CCMP2090." (PMID 31017983, 2019). "The expression of MYB TFs was observed after PXO99A and P99M2 infection in CBB23 at different time intervals." (PMID 30842619, 2019). "Five WRKY, four NAC, and MYB, three bHLH, two AP2-EREBP, G2-like, and one bZIP TF family were upregulated, and two TFs, namely, bHLH-161 and Homeobox-60/71, were downregulated in Fg, Fv, and Um infections." (PMID 36388593, 2022). "Based on previous studies, we speculate that MYB, AP2, WRKY and NAM may play important role in the infection of Rhizoctonia cerealis." (PMID 35534832, 2022). "Among these TFs, MYB, WRKY, and Ethylene-responsive transcription factor gene families are often reported to be involved in regulating general lignin biosynthesis or lignin accumulation upon pathogen infection in many other plant organisms." (PMID 35099559, 2022). "Moreover, several families of transcription factors were also found to be enriched in the set of genes that was upregulated in Trincadeira under infection (ZIM, WRKY, NAC, MYB, JAZ, ERF, and others)." (PMID 36479580, 2022). "Furthermore, several studies of the Xoo-rice interaction have observed that the expression of some rice MYB TFs, such as MYB51, R2R3-MYB and MYB4, were activated or upregulated in leaves at the early stage of PXO99A infection." (PMID 34176023, 2021).